TLR3 (toll like receptor 3)
Diseases named in the same sentence as TLR3 in open-access papers (continued):
Sharing a sentence is not in itself a finding about the gene and the disease.
tumor (continued). "Activation of TLR3 is necessary for coordinating the pro-apoptotic response mediated by CD103 + DCs, highlighting the pivotal role of TLR3 in coordinating a multifaceted anti-tumor immune response." (PMID 39988665, 2025). "In this study, we report for the first time that induction of ferroptosis in HCC by tumor infiltrated CD8+ T cells that atctivated by TLR3 signaling is the key mechanism for improving the abscopal effect of the combined treatment." (PMID 38671318, 2024). "Poly(I:C), a synthetic analog of viral double-stranded RNA (dsRNA), is a TLR3 agonist that induces efficient anticancer activity acting on macrophages, by promoting a switch from M2 to M1 phenotype, eventually reducing tumor growth." (PMID 38776331, 2024). "Conversely, TLR3 agonists directly inhibit tumour growth by decreasing growth signals and apoptosis induction." (PMID 38698968, 2024). "TLR-3 recognizes double-stranded RNA and induces antiviral responses, potentially promoting tumor cell apoptosis, although its role in GC requires further investigation." (PMID 39451226, 2024). "While some TLRs, such as TLR2 and TLR4, have shown both promotive and suppressive effects on tumor growth, others like TLR3 and TLR5 offer promising avenues for therapeutic intervention due to their more defined roles in enhancing anti-tumor immunity." (PMID 38903515, 2024). "Activation of lung epithelial TLR3 by RNAs in tumor-derived exosomes via NF-kB and MAPK pathways increased the production of chemokines such as CXCL1, CXCL2, CXCL5, and CXCL12, leading to the recruitment and accumulation of neutrophils for PMN formation." (PMID 38495881, 2024). "On the immunological front, CPE interacts with the innate immune system via TLR3, potentially influencing the tumor microenvironment and eliciting an anti-tumor response from the body." (PMID 39166136, 2024). "Targeting TLR3 is promising to stimulate protective anti-tumour immunity as an adjuvant therapeutic strategy." (PMID 38698968, 2024). "Conversely, TLR3 signaling also upregulates proinflammatory and anti-inflammatory cytokines, which support the immune tolerogenic status of the tumor." (PMID 38776331, 2024). "TLR3 also acts directly on tumour cells through stimulation with dsRNA and promotion of tumour cell apoptosis in various tumour cells, mediating TLR3-dependent cell apoptosis." (PMID 38698968, 2024). "For example, tumor cells were found to secrete EVs that carry snRNAs capable of activating Toll-like receptor-3 (TLR-3) in lung epithelial cells which induced chemokine secretion in the lung." (PMID 38765006, 2024). "Well-differentiated cSCCs had stronger TLR3 staining at the tumor edge than within the interior of the tumor, whereas moderately differentiated cSCCs had consistent TLR3 staining throughout the entire tumor." (PMID 39348939, 2024). "Overall, BCCs and cSCCs exhibit unique TLR3 staining patterns and intensities that are specific to their tumor types." (PMID 39348939, 2024). "The activation of TLR-2 and TLR-9 by PCa cells appears to promote tumour growth; conversely, the activation of TLR-3, TLR-5, and TLR-7 has been suggested as a potential way to prevent PCa." (PMID 39201739, 2024). "Activation of TLR3 signaling by poly(I:C) increased intra-tumoral chemokine expression, NK-cell activation, and proliferation of tumor-infiltrating T and NK cells, which contribute to increasing cell death and decreased tumor growth." (PMID 37020586, 2023). "Dying tumor cells have also been shown to release nucleic acids such as RNA that bind to toll-like receptor 3 (TLR3) and activate innate immune cells to secrete type-1 interferons (IFN-1s)." (PMID 37626741, 2023). "All this evidence indicates that TLR3 activation in a tumor and its microenvironment by endogenous ligands can induce tumor survival and progression." (PMID 36982351, 2023).
tumor (continued). "A study conducted using both mouse models and cell lines showed that primary tumor-derived exosomal RNAs mediate the activation of TLR3 in lung epithelial cells inducing chemokines release that in turn recruit neutrophils from bone marrow to the PMN site." (PMID 37207158, 2023). "At the same time, however, the EVs activated CD300a, which inhibited the TLR3-TRIF signaling, causing a decrease in Treg production and tumor growth." (PMID 38139035, 2023). "Comparable anti-tumor results were detected in mice models of Lewis lung carcinoma and sarcoma following induction of TLR3 and TLR4 mediated signaling, respectively." (PMID 37936697, 2023). "Wt and TLR3 KO NCI-H292 cells were used to further characterize the direct anti-tumor effect of TL-532." (PMID 37275475, 2023). "The activation of TLR3 enhances the anti-tumor effects of chimeric antigen receptor–modified T (CAR-T) cells." (PMID 37005579, 2023). "Regarding the capacity of TL-532 to induce TLR3-dependent inflammation and specific tumor-cell death, further animal studies will be necessary to confirm our in vitro observations." (PMID 37275475, 2023). "Another pre-clinical study shows an anti-tumor effect after treatment of mice with lung cancer or fibrosarcoma with the combination of a TLR3 agonist poly(I:C) and TLR8 agonists, R837 or R848." (PMID 37143666, 2023). "Beyond the possible involvement of TLR3 in the progression of HNSCCs, one merit of our study is that it shows that functional studies are possible on tumor necrotic fluids collected intraoperatively." (PMID 37894949, 2023). "Overall, our data converge with published data to support the idea that necrotic biomolecules released in the tumor microenvironment by malignant cells—especially dsRNAs—contribute to tumor growth through autocrine TLR3 stimulation." (PMID 37894949, 2023). "The use of a TLR3 agonist enhanced T cell infiltration in lung tissue, which is essential for tumor immunity within the tumor microenvironment (TME)." (PMID 37112730, 2023). "In this regard, it is interesting to note that TLR3 is frequently expressed by tumor cells in human malignancies." (PMID 37894949, 2023). "Again, tumor cell death occurred through apoptosis in a TLR3 dependent manner as shown using Bafilomycin A1." (PMID 37275475, 2023). "Activation of the TLR3 pathway was essential for the anti-tumor effects of poly (I:C), while TLR3+ Batf3 DCs and CD8+ T cells were indispensable for the therapeutic efficacy of poly (I:C)." (PMID 37112730, 2023). "TLR3-stimulating activity was detected in the fluids from all five patients and three mouse tumor grafts." (PMID 37894949, 2023). "Primary tumor releases tumor-derived exosomes, which contain small nuclear RNAs that can activate TLR3 in alveolar cells to produce chemokines and induce neutrophil infiltration." (PMID 36982351, 2023). "In a recent study, toll-like receptor 3 (TLR3) on lung epithelial cells is responsible for triggering neutrophil recruitment and lung pre-metastatic niches by sensing tumor exosomal RNA to induce secretion of chemokines (CXCL1, CXCL2, CXCL5, and CXCL12)." (PMID 37158964, 2023). "Wang and co-workers developed a vaccine strategy by using the mPEG-b-PLVal hydrogel as the scaffold to encapsulate tumor cell lysates (TCLs) and a toll-like receptor 3 (TLR3) agonist, polyinosinic:polycytidylic acid (poly(I:C))." (PMID 37265604, 2023). "Polyinosinic-polycytidylic acid and poly-L-lysine (Poly ICLC—Hiltonol), a TLR3 agonist, can activate immune cells and encourage their migration into the tumor mass." (PMID 37237548, 2023). "Tumor exosomal RNAs promote the chemokine secretion through activation of their Toll Like Receptor 3 on AT2 cells, which recruits neutrophils for lung pre-metastatic niche formation." (PMID 38033489, 2023). "It has also been demonstrated that tumor-derived circRNA can induce toll-like receptor 3 (TLR3), leading to stimulation of the NF-κB signaling pathway." (PMID 37753074, 2023).
tumor (continued). "In HCC, the suppression of TLR3 increased tumor proliferation, angiogenesis, and inhibited apoptosis of liver cancer cells." (PMID 37112730, 2023). "For cancer therapy, the ideal TLR3 agonist should trigger immunogenic tumor cell apoptosis and stimulate myeloid cells, thereby inducing anti-tumor immune response." (PMID 37275475, 2023). "On the flip side, in NSCLC, TLR3 has been observed in vitro to induce apoptosis of tumor cells and to activate lung DCs to elicit positive immune responses." (PMID 36389785, 2022). "Other inflammatory cytokines, such as toll like receptor 3(TLR-3), transforming growth factor β (TGF-β), IFN- α/β and IL-4/6/17/27 have been shown to enhance the expression of PD-L1 mRNA on tumor cells or tumor associated stromal cells." (PMID 36505487, 2022). "The addition of OX40/TLR3/9 immunotherapy to SBRT also resulted unexpectedly in T cell depletion from tumor tissues relative to animals treated with SBRT alone." (PMID 35055015, 2022). "In situ tumor vaccination with intratumoral injection of OX40 antibodies in combination with TLR3 or TLR9 agonists has been reported in rodent models to induce systemic antitumor immunity." (PMID 35055015, 2022). "TLR3 also promotes tumor elimination or indirectly promotes tumor progression through upregulation of interferon-α/β and NK cell activation." (PMID 36365103, 2022). "Tumor exosomal RNA contributes to host lung epithelial cell TLR3 activation, which is predominantly expressed by alveolar epithelial cells in pre-metastatic lung, inducing neutrophil recruitment and lung metastatic niche formation." (PMID 35739335, 2022). "Activation of TLR3 in alveolar epithelial cells is critical for initiating neutrophil recruitment and lung metastatic niche formation by sensing tumor exosomal double-stranded RNA (dsRNA)." (PMID 35739335, 2022). "TLR3 in TME is mainly expressed in Batf3-positive dendritic cells (DCs) (CD141+ DCs in human, CD8a+ and CD103+ DCs in mouse) and tumor associated macrophages (TAMs)." (PMID 35413927, 2022). "The prognostic value of TLR3 is also opposing and dependent upon its expression on tumor versus immune cells." (PMID 36389785, 2022). "For instance, before metastasis initiation, TLR3 signaling promotes tumor cell death in breast and lung cancer and also in head and neck squamous cell carcinoma." (PMID 36411434, 2022). "Our Western blotting data confirmed that Aza indeed enabled the high expression of TLR3 in tumor cells." (PMID 35805071, 2022). "One study suggests TLR3 is necessary for the immune response against ReoV, as knockdown of TLR3 with siRNA reduces the response both in cellulo and in tumor xenograft models." (PMID 35681452, 2022). "Tumor necrosis factor-α overproduction mediated by EBER/TLR3 pathway created a pro-tumorigenic microenvironment for tumor growth." (PMID 36551991, 2022). "In this study, GEPIA, DriverDBv3, UALCAN and TIMER databases were used to analyze the relationships between the expression of TLR3 in different tumor types and tumor prognosis." (PMID 36419829, 2022). "Here, we demonstrated that LP, a potent TLR2 and TLR3 agonist, can remodel the tumor immune microenvironment and enhance antitumor immunity." (PMID 35764365, 2022). "Among them, in situ vaccine with Flt3L/ radiotherapy/ TLR3 agonists had been demonstrated to upregulate PD1 expression on T cells by almost two-fold in the tumor microenvironment." (PMID 36463242, 2022). "Anthracycline-dependent production of type I IFNs was also demonstrated to be produced by tumor cells following activation of the TLR3-TICAM1 signaling pathway." (PMID 35292881, 2022). "TLR3 expression on tumor cells elicited favorable NSCLC outcomes during early stages, whereas TLR3 expression on immune cells, primarily macrophages, elicited poor prognosis in patients’ survival." (PMID 36389785, 2022).
tumor (continued). "In recent years, pre-clinical investigations of TLR3-targeted therapy have focused on combination therapy of TLR3 agonism with other treatment modalities, including chemotherapy, tumor vaccines, and ICB." (PMID 36479129, 2022). "This immunotherapy targets tumor-derived exosomes as potential antigens and uses TLR3 agonists to generate long-lasting T-cell immune effect and destroy the immune tolerance of the tumor." (PMID 36741380, 2022). "The PPI network and functional analysis of TLR3 and its interacting genes also proved the close relationship between TLR3 and tumor immune microenvironment." (PMID 36419829, 2022). "As sensors for dsRNA, tumor TLR3 promotes tumor cell survival, proliferation and chemotherapy resistance, or improves sensitivity to poly(I:C)-mediated cancer therapy." (PMID 35739335, 2022). "It was also demonstrated that EVs secreted by bone marrow DCs elicit improved anti-tumor activity upon Toll-like receptor 3 (TLR3) stimulation in DCs." (PMID 35805074, 2022). "GEGFR, CD40, SPATA2, ZBP1, ID1, and MYC showed a significant CNV amplification in most tumour types; however, TLR3, PDHB, FAS, and MAP3K showed a significant CNV deletion in most tumour types." (PMID 36186436, 2022). "TLR3 is one of the TLR targets that represents the potential of anti-tumor activity, and its expression is significantly increased in tumor tissues." (PMID 35413927, 2022). "It was found that tumor exosomal RNAs promoted lung metastatic niche formation by activating alveolar epithelial Toll-like receptor 3 (TLR3) to recruit neutrophils." (PMID 35719975, 2022). "LP simultaneously activated TLR2 and TLR3 signaling, thereby extensively changing the immune-related gene signatures within the tumor microenvironment (TME)." (PMID 35764365, 2022). "The emergence of this tumor suppressor function is that TLR3 can promote the apoptosis of cancer cells on the one hand, and on the other hand, it is also related to the induction of cytotoxic factors and the production of some interferons." (PMID 35664309, 2022). "A recent study has shown that tumor exosomal RNAs promote lung PMN formation by activating TLR3, which is predominantly expressed by alveolar epithelial cells in pre-metastatic lungs." (PMID 35739335, 2022). "In summary, we developed and optimized a formulation of tumor cell-specific exosomes (HELA-Exos) to specifically transfer the TLR3 agonist Hiltonol and the ICD inducer ELANE into tumor cells." (PMID 35148751, 2022). "Tumor cell-derived double-stranded RNA acts as an upstream signal to interact with RNA receptor TLR3 to induce endothelial SLIT2 expression." (PMID 36172371, 2022). "The results of our study and previous researches demonstrated that TLR3 was closely related to the tumor immune microenvironment, and this study provided an explanation for the different prognostic outcome of TLR3 in different cancers." (PMID 36419829, 2022). "The association between TLR3, TLR4, and TLR9 expressions and tumor aggressiveness and poor prognosis in HCC was obtained from 30 patients with HCC." (PMID 35434373, 2022). "Recent studies have demonstrated that administering a TLR3 agonist enhanced the maturation of CD8α+ DCs, which in turn promoted cross-presentation in the tumor microenvironment and tumor regression 54,55." (PMID 34975324, 2022). "In the lung environment, the TLR3 of lung epithelial cells can be activated by exosomal RNA derived from the primary tumor to stimulate the NF-κB, ERK, and p38 pathways to secrete chemokines." (PMID 35664309, 2022). "In the present study, we showed that TEV-stimulated DCs for IFN-β production via TLR3 at the endosomes, resulting in the increased number of tumor-infiltrating Treg cells and thus the exacerbation of tumor development." (PMID 34751648, 2021). "TLR3 treatment coincided with a type 1 interferon pathway gene signature, which was observed broadly within the tumor immune microenvironment." (PMID 34381732, 2021).
tumor (continued). "Meanwhile, it has been shown that Toll-like receptor 3 (TLR3) signaling can transform tumor-supporting TAMs into tumor suppressors by rapidly inducing the production of pro-inflammatory cytokines." (PMID 34603327, 2021). "Tumor-associated macrophages in HNSCC patients are associated with poor prognosis and are known to overexpress toll-like receptor 3 (TLR3)." (PMID 33809574, 2021). "TLR4-primed MSCs are called MSC1 that exhibited an antitumorigenic impact, while TLR3-primed MSCs are called MSC2 that had a tumor-supportive function." (PMID 34736460, 2021). "In an HCC mouse model, poly (I:C)-induced TLR3 signaling can lead to a reduction in tumor enlargement and decrease tumor growth and cell proliferation." (PMID 33986756, 2021). "Another experiment demonstrated that DEXs loaded OVA with poly(I:C), a ligand of TLR-3, induced a strong protective immune response and markedly inhibited the tumor growth and improved the survival rate of the tumor-bearing mice." (PMID 34513718, 2021). "As cDC1 cells most abundantly express TLR3 and were found to be the only major source of TLR3 within the tumor, our findings are consistent with DC-derived type 1 interferon-mediated polarization of the tumor immune microenvironment." (PMID 34381732, 2021). "Tumor exosomal RNAs participate in the pre-metastatic niche formation in the lung and induce neutrophil recruitment via-toll-like receptor 3 (TLR3) activation on alveolar epithelial type 2 cells, as demonstrated in TLR3 −/− mice." (PMID 33731188, 2021). "TLR3 promotes metabolic reprogramming of head and neck carcinoma cells and increases tumour growth and proliferation." (PMID 33336901, 2021). "Consistently, RAP99-LPS suppressed the lung metastasis of B16F1 tumor cells and enhanced the expression of TLR3-mediated chemokines." (PMID 34113349, 2021). "It has been shown that lung epithelial cells play a crucial role in the initiation of neutrophil recruitment and formation of lung metastatic niche by sensing tumor exosomal RNAs via toll-like receptor 3 (TLR3)." (PMID 34281588, 2021). "It has been suggested that TLR3 can force tumour cells to switch from oxidative phosphorylation (OXPHOS) to glycolysis, which subsequently increases the expression of the transcription factor HIF‐1α and regulates hypoxia." (PMID 33336901, 2021). "To further evaluate the impact of TLR3 on the level of immune cells infiltrating and tumor purity, we analyzed the correlation between TLR3 and the immune/stromal/ESTIMAT score." (PMID 34094905, 2021). "CD300a inhibits TLR3-mediated interferon-β (IFN-β) expression upon recognition of tumor-derived exosomes." (PMID 34751648, 2021). "To identify populations that respond to TLR stimulation within the tumor microenvironment, we assessed TLR3, 7 and 9 expression within clusters." (PMID 34381732, 2021). "TLR3/7/9−/− mice showed a delay in tumor regression and partial tumor volume reduction compared to WT mice." (PMID 34341449, 2021). "In this review, we focus on the “double-edged sword” roles of TLR3 in tumor initiation and progression." (PMID 33986756, 2021). "TLR3 is expressed primarily endosomal and in multiple cell and tissue types, including muscle cells, epithelial cells, certain neoplasms and antigen presenting cells; the RIG-I and MDA-5 are ubiquitously expressed." (PMID 34766005, 2021). "TLR3 stimulator poly I:C (a synthetic analog of viral dsRNA) increased production of type I IFNs and inhibited tumor cell proliferation, and ARNAX (DNA-capped dsRNA modulator, TLR3 agonist) increased CTL and memory cell numbers." (PMID 34124272, 2021). "In cancer vaccination, the use of the Toll-like receptor 3 (TLR3) agonist polyinosinic-polycytidylic acid (poly(I:C)) as an adjuvant has been shown to increase the number of CTLs targeting tumor antigens." (PMID 34553028, 2021).